INS (insulin)
Diseases named in the same sentence as INS in open-access papers (continued):
Sharing a sentence is not in itself a finding about the gene and the disease.
Hypoglycemia (continued). "For patients whose insulin dose was decreased by the investigator because of a hypoglycemic event, the incidence rate of hypoglycemia per subject-year exposure decreased with dose reduction in the canagliflozin group, regardless of the type of insulin regimen." (PMID 27316668, 2016). "Experimental insulin infusion can be used to induce severe hypoglycemia but in the presence of prolonged starvation does not induce ketoacidosis." (PMID 27458340, 2016). "Finally, this study did not address insulin stacking, which may also cause hypoglycemia." (PMID 26819233, 2016). "Sulfonylurea, a traditional hypoglycemic drug, promotes insulin secretion regardless of the blood glucose level; because of this, it risks eliciting serious hypoglycemia." (PMID 27491540, 2016). "Insulin degludec in the flexible schedule achieved non-inferiority and significantly reduced confirmed nocturnal hypoglycemia." (PMID 26740822, 2016). "Despite the limitation that no strict treatment protocol for glycaemic control was used, net glycaemia improved, TDD decreased with an average of 30 U/day with 30 % of patients stopping insulin and no severe episodes of hypoglycaemia." (PMID 26597956, 2016). "Initiated hypoglycemic therapy, including administration of insulin, was not significantly different between the groups of patients with and without episodes of hypoglycemia." (PMID 27246347, 2016). "In this patient, the insulin level during hypoglycemia (30 mg/dL) was 40 mIU/mL and no genetic analysis was made." (PMID 26758964, 2016). "The odds of a patient who was using insulin reporting hypoglycaemia was six times that of a patient not taking insulin." (PMID 27380790, 2016). "The use of sensor-augmented insulin pump therapy with the threshold-suspend feature has previously demonstrated a reducing nocturnal hypoglycemia effect without increasing HbA1c values in patients with documented nocturnal hypoglycemia." (PMID 28004007, 2016). "Though widely prescribed, neither basal insulin nor sulfonylureas should be recommended as second-line options if avoidance of drug-induced hypoglycemia is of priority." (PMID 27648831, 2016). "Often, however, the medical team responds inadequately, and insists on increasing the insulin dose, which the patient reduces without reporting the decrease because of fear of worsening hypoglycemia." (PMID 27471550, 2016). "Our data demonstrated that when combined, glucose and insulin injections, without subsequent hypoglycemic episodes, do not result in acute painful neuropathy, suggesting that insulin itself does not induce hypoglycemia-induced mechanical hypersensitivity." (PMID 26824041, 2016). "Insulin was administered in five (18.52 %) patients with hypoglycemic episodes and in seven (14.00 %) patients without hypoglycemia." (PMID 27246347, 2016). "As one of the most common causes of severe hypoglycaemia in the ICU is a reduction in, or switching off of nutrition without proper adjustment of the rate of insulin, this connection is crucial to safety." (PMID 26801983, 2016). "There was one patient with severe hypoglycemia, increased serum insulin and C-peptide concentrations and negative result of GLP-1 scintigraphy." (PMID 27526057, 2016). "With insulin therapy, further improvement is needed for a glycemic control that will not increase hypoglycemia and weight gain to limit the insulin dose when high doses are needed." (PMID 26798658, 2016). "The diagnosis was based on the presence of inappropriately high levels of insulin, non-ketotic hypoglycemia, and a raised demand for glucose in order to prevent hypoglycemia." (PMID 27065949, 2016). "According to another report, vagal withdrawal and augmented sympathetic activities are common during periods of hypoglycemia regardless of insulin level." (PMID 27441373, 2016).
Hypoglycemia (continued). "In healthy, non-diabetic humans, hypoglycemia is unlikely to ever occur due to a hierarchically coordinated system that integrates insulin secretion and counterregulatory hormone and symptom responses." (PMID 26521082, 2016). "If there was no previous evidence of either taking drug affecting insulin secretion or any critical illnesses (i.e. hepatic, renal or cardiac failure or severe infection), the management of such patients is still challenging for clinicians as hypoglycemia might be caused by many reasons." (PMID 27526057, 2016). "With typical Whipple triad and a high serum insulin level, the diagnosis of pancreatogenous hypoglycemia is not difficult." (PMID 27367988, 2016). "On the other hand, those who received assistance from family members with the insulin injection had a 0.5-fold (25.6% vs. 50.0%, p = 0.013) proportion of patients who experienced mild hypoglycemia, compared with those with no family assistance." (PMID 26102197, 2015). "Few available drugs can enhance β-cell viability and restore their ability to synthesize and secrete insulin without side effects such as hypoglycemia or weight gain." (PMID 26351642, 2015). "Furthermore, longer insulin treatment and previous TIA/stroke were related to increased odds of having hypoglycemia." (PMID 25698911, 2015). "Since incretin hormones stimulate insulin secretion in a glucose-dependent manner, DPP-4 inhibitors improve hyperglycemia without an increase in risk of hypoglycemia and weight gain." (PMID 25816296, 2015). "Three patients developed mild hypoglycemia (one patient in the NAFLD group receiving sulfonylurea, one patient in the ALD group receiving insulin, and 1 patient in the LC group receiving sulfonylurea), but no severe cases of hypoglycemia were seen in this study." (PMID 26191473, 2015). "In none of the studies did hypoglycemia lead to withdrawal, and it predominantly occurred when dapagliflozin was used with a sulfonylurea or insulin." (PMID 26474563, 2015). "As expected from a true insulin sensitizer, Cmpd1 does not increase hypoglycemia as an IR activator would." (PMID 25799496, 2015). "HAAF is characterized by lack of suppression of endogenous insulin secretion and failure of glucagon and catecholamine secretion during hypoglycemia." (PMID 26343738, 2015). "Due to the higher number of patients not reaching target glycemic control, previously reported differences in incidence of hypoglycemia when comparing insulin glargine and NPH insulin were not shown in the present study." (PMID 26055391, 2015). "Hypoglycaemia rates (any with or without help and symptoms) were higher for patients receiving insulin (Odds Ratio [OR] 8.35; 95% Confidence Interval [CI] 4.84-14.4) and Met/SU (OR 2.70; 95% CI 1.48-4.92) versus Met/Incr." (PMID 25645672, 2015). "The results show that in a patient population with sub-optimal glycemic control at baseline, and a low target achievement rate together with a low rate of hypoglycemia, differences in the patient reported outcomes evaluated in this study were negligible between insulin glargine and NPH insulin." (PMID 26055391, 2015). "Testing for insulin antibodies and oral hypoglycemics was negative and a 72-hour fast was completed without hypoglycemia." (PMID 26523235, 2015). "Seven weeks after discontinuing her preprandial short-acting insulin her HbA1c remained at 6.6% and she had not had any episodes of hypoglycemia." (PMID 25785209, 2015). "Ten-day-old rats (neurodevelopmentally equivalent to a human term newborn infant) do not mount a robust corticosterone response to insulin-induced hypoglycemia, despite increased ACTH secretion, suggesting that the defect is at the level of adrenal cortex." (PMID 26343738, 2015). "Additional adjustment for insulin did not change the significantly higher event rate of severe hypoglycemia in psoriasis patients (0.23 [0.177; 0.297] versus 0.05 [0.048; 0.051] per patient year, p < 0.0001)." (PMID 26357664, 2015).
Hypoglycemia (continued). "Patients with depression were more likely to report hypoglycemia during the previous 3 months than those without depression (37.9% vs 18.1%, P < 0.001), despite comparable use of sulphonylurea and insulin." (PMID 25349949, 2015). "Adding sitagliptin to insulin reduced HbA1c without weight gain or increase in hypoglycemia, and improved treatment satisfaction in Japanese patients with T2DM who were suboptimally controlled despite at least twice daily injection of insulin." (PMID 25816296, 2015). "Metformin has advantages over insulin such as less maternal weight gain, no maternal hypoglycemia, being cheap, being oral therapy, and requiring no vigorous monitoring and frequent hospital admissions with good compliance and acceptability." (PMID 25874236, 2015). "As shown in case 3, the addition of an SGLT2 inhibitor to the basal-bolus insulin regimen resulted in lower doses of preprandial rapid-acting insulin being utilized leading to less hypoglycemia and improved though not ideal glycemic control." (PMID 25785209, 2015). "The remaining case had a paternal duplication similar to our patient, but neither insulin nor ketones were measured at the time of hypoglycaemia." (PMID 26631065, 2015). "Hypoglycemia has been correlated with higher weight-based insulin doses in other studies, but this was not the case in this analysis." (PMID 26594250, 2015). "MET+ SU+ TZD, MET+ SU+ DPP-4-i and MET+ SU+ insulin had increased odds ratio of hypoglycaemia, while MET+ SU+ GLP-1-RA did not significantly increase the odds ratio (1.61; 95% CI [0.90–2.87]), when compared to MET+ SU." (PMID 26664803, 2015). "On the other hand, those who received assistance from family members with the insulin injection had a 0.2-fold (8.6% vs. 36.2%, p = 0.004) proportion of patients who experienced severe hypoglycemia, compared with those with no family assistance." (PMID 26102197, 2015). "Patients receiving rosiglitazone showed weight gain, a major side effect of TZDs, whereas insulin sensitivity was not significantly different and the incidence of hypoglycemia was not lower." (PMID 26273677, 2015). "The decrease level of C-peptide in our case suggested that the patient did not develop hypoglycemia secondary to insulin secretion by the pancreas, but the presence of a substance that mimicked the effects of insulin was highly suspected." (PMID 26839722, 2015). "The level of insulin achieved during hypoglycaemia is not indicative of the severity of the condition." (PMID 26316429, 2015). "Adding sitagliptin resulted in a 0.6% reduction in HbA1c without an increase in incidence of hypoglycemia compared with the control group in which insulin dose was up-titrated by 25% during the study." (PMID 25816296, 2015). "Higher plasma levels of von Willebrand factor with increased blood viscosity have been documented in response to insulin-induced hypoglycemia without any changes in fibrinogen or fibrin degradation products." (PMID 25928628, 2015). "Overall, 71.5% patients responded positively to the question, “Do you know what hypoglycemia is?”: 91.4% patients receiving insulin therapy, 75.8% using SU agents, and 64.3% not using insulin or SU agents." (PMID 26566411, 2015). "This study indicates that lack of assistance from family members at the time of insulin injection and receiving intensive insulin therapy were predictors for severe hypoglycemia." (PMID 26102197, 2015). "A number of studies have examined the effects of insulin-induced hypoglycemia on CBF, some of which reported small or no changes, but most found significant increases in CBF." (PMID 26528968, 2015). "During the 72-hour fast, which he completed without hypoglycemia, insulin declined to be within normal limits (to 12 μIU/mL); proinsulin (to 12.1 pmol/L) and C-peptide (to 7.2 ng/mL) levels decreased but remained elevated." (PMID 26664768, 2015).
Hypoglycemia (continued). "As expected, insulin injection induced hypoglycaemia both in the insulin group and in the glucose plus insulin group, but not in the other three groups." (PMID 26366172, 2015). "Even greater elevations over Met/Incr were seen for symptomatic hypoglycaemia without the need for help (insulin OR 11.45; 95% CI 5.90–22.2 and Met/SU OR 3.13; 95% CI 1.46–6.99)." (PMID 25645672, 2015). "Surprisingly, even hypoglycaemia on prior oral therapy did not prevent physicians from introducing an insulin-based treatment strategy." (PMID 25645672, 2015). "Another possibility that was postulated was the stimulation of the pancreas by the tumor to secret insulin but an autopsy series by Hart and Hinerman revealed pancreatic islet cell hyperplasia in eight cases of Hodgkin's disease without hypoglycemia." (PMID 26839722, 2015). "We entertained the possibility of an insulin antibody mediated hypoglycemia in light of his multiple myeloma history; however, insulin antibody was not detectable." (PMID 26664768, 2015). "In conclusion, adding sitagliptin to insulin reduced HbA1c level by 0.9% without weight gain or increase in hypoglycemia, and improved treatment satisfaction in Japanese patients with suboptimally controlled T2DM." (PMID 25816296, 2015). "Assistance from family members at the time of insulin injection [presence/absence, OR (95% CI): 0.19 (0.05–0.75)] and intensive insulin therapy [yes/no, OR (95% CI): 3.61 (1.06–12.26)] affected severe hypoglycemia." (PMID 26102197, 2015). "Even 8-day-old neonatal rats mount ACTH and corticosterone response during insulin-induced hypoglycemia, although the response is not as robust as in older rats (P19 and beyond)." (PMID 26343738, 2015). "Yet over three-quarters of apps did not offer a mechanism for reducing postprandial boluses to reflect residual insulin activity, and one in six did not reduce dose recommendations in response to hypoglycemia." (PMID 25943590, 2015). "Instead, the reduced frequency of hypoglycemia in CSII and flexible basal insulin adjustment might encourage the patients to perform exercise more regularly." (PMID 25802842, 2015). "The proportions of patients with hypoglycemia (defined as events in conjunction with a blood glucose measurement of <3.1 mmol/L) were 17.7 % during treatment with insulin glargine and 15.8 % during treatment with NPH insulin." (PMID 26055391, 2015). "Our IPITT data further indicated a great improvement of insulin sensitivity in TO-treated db/db mice without the risks of hypoglycemia." (PMID 25909991, 2015). "Although endogenous insulin production is normally suppressed in the setting of hypoglycemia, the lack of suppression during a 72-hour fast is a strong indicator of the presence of an insulin-secreting tumor." (PMID 25816027, 2015). "In the nonexercised animals (GC and GR), hypoglycaemia was already present 15 min after insulin injection and its lowest values were recorded at 60 and 120 min." (PMID 24719616, 2014). "This procedure has the advantage of avoiding certain shortcomings in insulin transport through the BBB, added to the fact it does not produce hypoglycemia, as sometimes happens after peripheral insulin administration." (PMID 25346723, 2014). "Due to their unique insulin-independent mechanism of action, SGLT2 inhibitors lower blood pressure and improve glycemic control, while at the same time avoiding potential risks of increased insulin doses such as hypoglycaemia, hypertension and weight gain." (PMID 24475922, 2014). "Patients were enrolled for varying reasons including lack of efficacy of premixed insulin (7% < HbA1c < 10%), wanting a more flexible lifestyle, frequent occurrence of hypoglycemia with previous therapy, and lack of tolerability of the previous therapy." (PMID 24620742, 2014). "Insulin was unlikely to have played a central role, as no episodes of hypoglycemia were observed under administration of the same dosages of insulin before admission." (PMID 24524438, 2014).
Hypoglycemia (continued). "At the time of hypoglycemia, insulin and C-peptide levels were not high: 4.3 uIU/mL and 0.1 ng/mL, respectively." (PMID 25541899, 2014). "This argues for insulin mediated reductions in fetal plasma mannose to extremely low concentrations (~8 μmol/L) independent of concurrent hypoglycemia." (PMID 24917928, 2014). "Thus, IGF-1 is known to enhance insulin sensitivity in humans and recombinant IGF-1 induces hypoglycemia as does its ectopic secretion." (PMID 24736741, 2014). "The attenuation of insulitis corresponded with preservation of beta cell mass with no corresponding increase in insulin and no hypoglycemia." (PMID 25259810, 2014). "Accumulating literature supports screening for IGF-2 in non-diabetic individuals who present with hypoglycemia along with suppressed insulin and c-peptide levels." (PMID 24934576, 2014). "The basal insulin analogue glargine has a long duration of action (approximately 24 h), with little or no discernible peak in blood insulin concentration, and a lower rate of hypoglycemia." (PMID 24620742, 2014). "Everolimus therapy was not interrupted and hypoglycemia was controlled irrespective of disease progression and further increase in insulin levels." (PMID 25298880, 2014). "Nigerian insulin requiring diabetics possessed poor knowledge of insulin use and are not conversant with some important terms such as ketoacidosis, insulin reaction and hypoglycemia." (PMID 24397956, 2014). "Using an insulin‐treated model of T1DM, the purpose of the present study was to investigate the cardiovascular benefit of several different exercise regimes which have been previously shown clinically to minimize the onset of hypoglycemia evoked by exercise." (PMID 25413321, 2014). "Since, there were only 6 episodes of hypoglycemia in 3 patients in insulin non-naïve group, we did not assess them in the univariate analysis." (PMID 24528773, 2014). "The effect of NO in relation to hypoglycaemia has never been reported before due to the neutralization of dermcidin isoform 2, a universal inhibitor of nitric oxide synthases via the hepatic insulin synthesis." (PMID 24711743, 2014). "To determine whether hypoglycemia might be due to ectopic insulin production, we examined RNA from a variety of DTG mouse tissues after 3 days of Dox (D3 DTG) for insulin transcripts." (PMID 24613355, 2014). "Administration of exogenous leptin or insulin (at low doses not inducing hypoglycaemia) brings about (at least short-term) reductions in food intake and body weight." (PMID 25119860, 2014). "The diagnosis is confirmed by the presence of non-suppressed insulin levels in presence of low glucose levels (see “Spontaneous hypoglycemia”)." (PMID 25038902, 2014). "EMD008 was chosen to reduce blood sugar levels rather than insulin or metformin to avoid any insulin-induced hypoglycemia and lactic acidosis, respectively." (PMID 26266919, 2014). "Surreptitious administration of insulin should not be excluded in diabetic patients with hypoglycemia without taking into account the rate of cross-reactivity of insulin analogues with the insulin assay used." (PMID 25541899, 2014). "Metformin does not increase insulin secretion from the pancreatic beta-cells and hypoglycemia and weight gain are minimal." (PMID 26237392, 2014). "Provocative tests: Biochemical diagnosis is based on lack of suppression of endogenous insulin secretion by hypoglycemia and inappropriately elevated insulin level during hypoglycemia is the diagnostic key point." (PMID 25038902, 2014). "Using these assays, we first demonstrated that high levels of insulin analogue, NovoRapid, were detectable during episodes of hypoglycaemia, although this was not administered on the same day." (PMID 24711924, 2014). "In the current analysis, more women versus men and more patients treated with OAD plus insulin versus sulfonylurea without insulin or nonsulfonylurea OAD without insulin reported hypoglycemia." (PMID 25433668, 2014).